LIFR (LIF receptor subunit alpha)
Diseases named in the same sentence as LIFR in open-access papers (continued):
Sharing a sentence is not in itself a finding about the gene and the disease.
leiomyoma (1 paper, 2022). A well-circumscribed benign smooth muscle neoplasm characterized by the presence of spindle cells with cigar-shaped nuclei, interlacing fascicles, and a whorled pattern. "The expression of EGFLAM-AS1 in leiomyomas was upregulated; EGFLAM-AS1 is a tumor suppressor in many cancers through its targeting leukemia inhibitory factor receptor (LIFR) which is a known metastasis inhibitor." (PMID 35641855, 2022).
liver neoplasm (1 paper, 2025). Tumors or cancers of the LIVER. "This lack of overlap prompted us to conduct a literature search in which we discovered a LIFR-centered molecular axis vulnerable to ferroptosis in ovarian and liver neoplasms among sources not text-mined by ENQUIRE." (PMID 39932993, 2025).
malaria (1 paper, 2021). Malaria is a serious and sometimes fatal disease caused by a parasite that commonly infects a certain type of mosquito which feeds on humans. "The severe malaria K-TSPs model identified ten gene pairs capable of differentiating severe from non-severe malaria including: SLC38A2-SCML1, SLC25A40-MAP2K7, DNALI1-AGPAT3, LIFR-TBCD, STK17B-ORC2, SF3B1-USP48, ZNF148-ZCCHC2, CBX5-CHAF1A, CNOT7-PLXNA2, and CREM-IDH1." (PMID 34746025, 2021).
medulloblastoma (1 paper, 2015). A malignant, invasive embryonal neoplasm arising from the cerebellum. "Among these genes, the leukemia inhibitory factor receptor α (LIFR α) was validated as a novel p110α target in medulloblastoma." (PMID 25915540, 2015). "More than 40 possibilities were found (data not shown), providing a hint that c-Myc may bind to the promoter of LIFR also in medulloblastoma." (PMID 25915540, 2015). "Since c-Myc is well known miRNA regulator in medulloblastoma and to this date LIFRα transcriptional regulation is very poorly studied we hypothesized, a c-Myc-dependent indirect control of LIFR expression via miRNA." (PMID 25915540, 2015).
myeloid leukemia (1 paper, 2015). A clonal proliferation of myeloid cells and their precursors in the bone marrow, peripheral blood, and spleen. "Further, LIFr is required for STAT3 activation to induce myeloid leukemia cell differentiation and growth arrest; the cytoplasmic domain of LIFr is capable of STAT3 signal transduction even when LIFr forms a homodimer." (PMID 26329521, 2015).
nasal polyp (1 paper, 2023). "We confirmed the mRNA expression of the IL-6 receptor (comprising IL-6R and gp130 chains) and the type II OSM receptor (comprising OSMR and gp130 chains) but not the type I OSM receptor (comprising LIFR and gp130 chains) in nasal polyp-derived HNECs." (PMID 37047067, 2023).
neuroblastoma (1 paper, 2025). Neuroblastoma (NB) is the most common solid, extracranial childhood tumor.
Osteopenia (1 paper, 2014). Osteopenia is a term to define bone density that is not normal but also not as low as osteoporosis. "Taken together, loss of LIF and CT-1 signaling in STWS due to the absence of a functional LIFR most likely contributes to osteopenia and bone-specific traits seen in STWS." (PMID 24618404, 2014). "Therefore, in STWS, the lack of OSM signaling through LIFR:gp130 receptor complex is not able to contribute positively to bone formation, and, in addition, OSM signaling mediated by OSMR:gp130 promotes bone resorption, thus playing a role in osteopenia." (PMID 24618404, 2014).
pancreatic ductal adenocarcinoma (1 paper, 2021). An infiltrating adenocarcinoma that arises from the epithelial cells of the pancreas. "LIF is a key paracrine factor from stromal cells acting on cancer cells; and LIF blockade or genetic LIFR deletion slows tumor progression, and augments the efficacy of chemotherapy to prolong survival of pancreatic ductal adenocarcinoma [PDAC]." (PMID 34400617, 2021).
periodontitis (1 paper, 2022). An acute or chronic inflammatory process that affects the tissues that surround and support the teeth. "We identified the CHEMERIN, HGF, IFN-I, IL16, LIFR, and APELIN pathways as not being active during homeostasis but rather, to be active in periodontitis." (PMID 36193890, 2022).
peripheral nerve injury (1 paper, 2019). Injury to a peripheral nerve. "As LIF expression is up regulated after peripheral nerve injury, observed down regulation of LIFR for at least 2 weeks may prevent non-neuronal cells from undesired consumption of LIF." (PMID 31139050, 2019).
polycystic ovary syndrome (1 paper, 2024). A disorder that manifests as multiple cysts on the ovaries. "Consistent with previous studies, our research shows a downregulation of LIFR in tissues from patients with polycystic ovary syndrome (PCOS), suggesting that LIFR may influence ovarian function and embryo development by modulating the ER stress response." (PMID 39850756, 2024).
prostate tumor (1 paper, 2024). "Our study shows that the activation of the leukemia inhibitory factor (LIF)/LIF receptor (LIFR) pathway in both prostate tumor and stromal cells, following androgen deprivation therapy (ADT), leads to the development of an immunosuppressive TME." (PMID 38381121, 2024).
renal carcinoma (1 paper, 2025). A carcinoma arising from the epithelium of the renal parenchyma or the renal pelvis. "Recent studies have demonstrated that LIFR inhibition with EC359 induces ferroptosis in renal cancer cells by inactivating GPX4 and depleting GSH." (PMID 40075639, 2025).
synovial sarcoma (1 paper, 2022). "Compared with the control tissues (chronic synovitis), the mRNA expression of SOX-2, Nanog, OCT-4, LIF, LIFR and Ki-67 was significantly higher in the synovial sarcoma tissue samples (P = 0.0070, P = 0.0487, P = 0.0002, P = 0.0110, P < 0.0001, and P = 0.0011, respectively)." (PMID 35151264, 2022).
tumor (97 papers, 2009 to 2026). "LIFR expression was positively correlated with the abundance of cancer-associated fibroblasts (CAFs) and endothelial cells in the tumor microenvironment." (PMID 36925915, 2023). "The LIF/LIFR axis is implicated in tumor growth and progression by acting on multiple aspects of cancer biology." (PMID 36358818, 2022). "The LIF/LIFR axis is implicated in tumor growth and progression by altering the magnitude of several oncogenic processes." (PMID 34400617, 2021). "We found that LIFR expression in GBC tissues was closely associated with tumor size (P = 0.035), as was PIK3R1 (P = 0.040)." (PMID 31119098, 2019). "One of the potential causes leading to the diverse LIFR expression in human malignancies is the presence of agonist or antagonist in tumor microenvironment." (PMID 30504771, 2018). "The detailed mechanism underlying the tumor suppressive effects of LIFR requires further investigation." (PMID 25749520, 2015). "It is not only highly mutated and overexpressed in tumor patients but also promotes the proliferation and metastasis of PCa through various mechanisms, including activation of the leukemia inhibitory factor receptor (LIFR), Kruppel-like factor-4 (KLF4) and antioxidant pathways." (PMID 41247636, 2025). "Additionally, LIF and LIFR expression levels are higher in GC cells compared to normal tissue and have been linked with tumor differentiation, increased lymph node metastasis, and higher rates of lymphovascular invasion." (PMID 41163398, 2025). "GAS5 could suppress the decrease of LIFR caused by miR-21 and rescue the function of LIFR on tumor cell viability." (PMID 36062165, 2022). "Interestingly, overexpression of PTHrP in MCF-7 cells downregulates tumor dormancy genes, including the tumor suppressor leukemia inhibitory factor receptor (LIFR), in part through close association with the DNA in the LIFR promoter region." (PMID 37345007, 2023). "In contrast, the loss of STAT3 signaling facilitates escape from dormancy, downregulates LIFR expression, and promotes tumor proliferation and colonization." (PMID 41596432, 2026). "In the nucleus, nPAK4 suppresses the expression of leukemia inhibitory factor receptor (LIFR), a key ERα target gene responsible for maintaining the dormant state of disseminated tumor cells (DTCs) in the bone marrow niche." (PMID 41596432, 2026). "Emerging evidence from pancreatic cancer models shows that stromal-derived LIF acts in a paracrine manner to promote tumor progression, and that LIFR blockade enhances response to chemotherapy." (PMID 41154625, 2025). "Our findings indicate that BC can target LIFR in hCMEC/D3 cells via exosomal miR-221-3p, thereby promoting glycolysis and inhibiting the expression of tight junction proteins, which facilitates tumor metastasis." (PMID 41272827, 2025). "The LLPS microenvironment driven by the two LCDs of KMT2D facilitates H3K4 histone monomethylation transcription as well as the expression of the tumor-associated TFs LIFR and KLF4, promoting tumor progression." (PMID 40642070, 2025). "In this context, the LIF/LIFR signaling axis represents a compelling and understudied pathway involved in tumor growth, immune evasion, and therapeutic resistance." (PMID 41163398, 2025). "Elevated expression of LIF, LIFR correlates with reduced survival in OCa patients and contributes to chemoresistance and tumor microenvironment (TME) modulation." (PMID 41154625, 2025). "The role of LIF/LIFR signaling in the tumor microenvironment (TME) is a topic of growing interest, particularly its interactions with immune cells and transcriptional regulators." (PMID 41163398, 2025). "This review aims to provide a comprehensive analysis of the current understanding of LIF and LIFR in the context of GC, highlighting molecular mechanisms of action, contributions to tumor progression, and potential as therapeutic targets." (PMID 41163398, 2025).
tumor (continued). "In conclusion, our findings indicate that BC can target LIFR in hCMEC/D3 cells via exosomal miR-221-3p, thereby promoting glycolysis and inhibiting the expression of tight junction proteins, which facilitates tumor metastasis." (PMID 41272827, 2025). "Our findings, derived from the analysis of public cancer databases alongside 32 established, primary OCa cell lines, and tumor tissues reveal the existence of an autocrine loop involving LIF/LIFR." (PMID 38789520, 2024). "Among these genes, overexpressed LIFR has previously been reported as an important cancer-related gene involved in tumor growth, metastasis, and therapy resistance." (PMID 39127727, 2024). "LIF/LIFR signaling plays a key role in tumor growth, progression, metastasis, stemness, and therapy resistance." (PMID 39518071, 2024). "LIFR-KO resulted in significant reduction in tumor volume (~58% reduction), tumor weights and tumor nodules." (PMID 38789520, 2024). "In summary, our data indicates that pharmacological inhibition of a positive autocrine loop of LIF/LIFR promotes ferroptosis and can inhibit OCa proliferation in vitro and tumor progression in vivo." (PMID 38789520, 2024). "A LIF blockade or genetic LIFR deletion slow tumor progression and augment the efficacy of chemotherapy." (PMID 39518071, 2024). "LIFR silencing markedly impaired tumor formation and decreased CSCs frequency in vivo, accompanied by diminished SOX2, CD44 and ALDH1A1 expression in samples." (PMID 39206755, 2024). "Our research underscores the importance of the LIF/LIFR autocrine loop for OCa cell survival, stemness, tumor immunity, and progression." (PMID 38789520, 2024). "The bioinformatics data showed the decreased expression of LIFR in tumor tissues compared with normal tissues, and we identified the downregulated expression of LIFR in our collected clinical samples." (PMID 36925915, 2023). "Here, we comprehensively analyzed the expression profile and prognostic value of LIFR, and correlations between LIFR and the infiltration of immune cells and clinicopathological parameters across different tumor types using several bioinformatic tools." (PMID 36925915, 2023). "The expression profile of LIFR in various tumor types and clinical stages was investigated using the TIMER2 and GEPIA2 databases." (PMID 36925915, 2023). "To identify the possible role of LIFR in carcinogenesis, we first assessed the differential expression of LIFR in different cells from normal and tumor tissues." (PMID 36925915, 2023). "Leukemia inhibitory factor (LIF) exhibits significant tumor-promoting function, while its cognate receptor (LIFR) is considered to act as either a tumor promoter or suppressor." (PMID 36925915, 2023). "We comprehensively analyzed the profiles of LIFR expression in various tumor types in TCGA database." (PMID 36925915, 2023). "It is possible that autocrine loops of cytokines such as LIF/LIFR in the tumor microenvironment induce multiple-cell survival and thus contribute to the low efficacy of the approved therapies." (PMID 38139260, 2023). "The LIF/LIFR axis plays a central role in tumour growth and progression, regulating key aspects of cancer biology including cancer cell growth, proliferation, migration and chemotherapy resistance." (PMID 36998446, 2023). "Based on the results surveyed here, LIFR expression in BRCA tumor tissues is clearly lower than in the corresponding normal tissues." (PMID 36925915, 2023). "The LIF receptor complex, composed of LIF, LIFR, and glycoprotein 130 (gp130), is responsible for promoting tumor growth, progression, and metastasis through the direct effect of JAK/STAT3 and other downstream pathways, such as MAPK, AKT, and mTOR." (PMID 37103052, 2023). "On the contrary, in the low-risk group, the expressions of IL3RA, CX3CR1, ARRB1, LIFR, and VIPR1 were higher than those in the high-risk group, which signified that they have a tumor suppressor effect." (PMID 35833114, 2022).
tumor (continued). "LIF is aberrantly secreted by tumour cells and promotes tumour progression in pancreatic and other solid tumours through aberrant activation of the LIF receptor (LIFR) and downstream signalling that involves the JAK1/STAT3 pathway." (PMID 36359879, 2022). "Another study identified that tumour suppressor lncRNA-CTD-2108O9.1 inhibits metastasis by targeting LIFR (Leukemia inhibitory factor receptor) gene." (PMID 36685962, 2022). "High levels of expression of LIFR mRNA in tumor tissues predict poor prognosis and reduced response to therapy." (PMID 35847866, 2022). "Another difference between both approaches is the classification of the driver gene LIFR, which is a known tumor suppressor gene." (PMID 36228003, 2022). "To explore the role of LIFR and LIF in GC, we have then assessed LIFR expression in 31 tumor samples from patients with GC and compared them to the corresponding non-neoplastic mucosa." (PMID 35847866, 2022). "The ESTIMATE score, combination of stromal and immune score, indicated that high expression levels of LIFR, ARHGAP24, and ELOVL5 were significantly associated with lower tumor purity, whereas CBX3 exerted an inverse effect." (PMID 33463006, 2021). "More specifically, as LIFR is down‐regulated by miR‐3682‐3p and less M1 macrophages infiltrate into TME, the ability of EC progression was enhanced, suggesting the role of LIFR in tumor progression." (PMID 33463006, 2021). "ESTIMATE score demonstrated that high expression levels of LIFR, ARHGAP24, and ELOVL5 were significantly associated with lower tumor purity, whereas CBX3 exerted an inverse effect." (PMID 33463006, 2021). "Western blot analysis of tumor lysates showed that PDX mice treated with HDACi have increased expression of LIFR." (PMID 34716410, 2021). "Further, the tumor weights are significantly lower in LIFR-KO groups compared to the vector control group." (PMID 34400617, 2021). "Recent studies showed that LIFR expression is upregulated during tumor progression of many cancers and contributes to therapy resistance." (PMID 34716410, 2021). "LIF and LIFR are overexpressed in multiple solid tumors and LIF/LIFR signaling promotes tumor growth, metastasis, and therapy resistance." (PMID 34400617, 2021). "Another study using a soluble version of the LIFR as a ligand trap demonstrated that blocking of LIF signaling slows tumor progression in a mouse model of pancreatic cancer." (PMID 34716410, 2021). "According to the existing studies and analyses, LIFR is highly expressed in CRC tumor tissues, which is related to the overall 5-year survival rate after surgery and plays the role of a carcinogen." (PMID 33505963, 2020). "In this study, we showed that tumor formation in the LIFR immunized group happened in only 25% of mice." (PMID 32651426, 2020). "Our findings indicated that immune-mediated blockage of LIF and LIFR delayed or event prevented tumor growth." (PMID 32651426, 2020). "In pancreatic cancer, a blockade of LIF:LIFR:STAT3 signaling resulted in a decrease in the expression of CSC-associated markers (CD133, CD24, and CD44), a reduction in tumor initiation and formation, and an overall less aggressive phenotype." (PMID 32023849, 2020). "In conclusion, according to the findings of this study LIF and LIFR can be considered in cancer targeted therapy, especially to fight with those tumors that express these proteins such as tumor-initiating cells." (PMID 32651426, 2020). "LIFR expression has further been proposed as a biomarker for the differentiation of HCC from dysplastic nodules, showing that LIFR expression decreases as the tumor cells progress from low-grade dysplastic nodules to HCC." (PMID 31683891, 2019). "Decreased LIFR expression correlated with a poor prognosis (P = 0.028) and was related to tumor size (P = 0.035)." (PMID 31119098, 2019).